CCNO (cyclin O)
Description:
Specifically required for generation of multiciliated cells, possibly by promoting a cell cycle state compatible with centriole amplification and maturation. Acts downstream of MCIDAS to promote mother centriole amplification and maturation in preparation for apical docking.
Synonyms: UDG2; FLJ22422; UNG2; CCNU; CILD29
Tractability: Small molecule: a high-quality ligand is known. PROTAC: ubiquitination databases record sites on it; a small molecule that binds it is known.
Target class: Kinase; Protein kinase regulatory subunit; Enzyme
Gene: Protein-coding gene on chromosome 5 (55,231,152 to 55,233,608, reverse strand). Ensembl gene ENSG00000152669.
Subcellular location: Cytoplasm; Nucleus, nucleolus
Subcellular location (Human Protein Atlas): Nucleoli; Nucleoplasm; Centriolar satellite
Gene Ontology:
Molecular function: protein binding; cyclin-dependent protein serine/threonine kinase regulator activity
Biological process: cilium assembly; mitotic cell cycle; multi-ciliated epithelial cell differentiation
Cellular component: cytoplasm; nucleolus; cyclin-dependent protein kinase holoenzyme complex; microtubule organizing center
Genetic constraint (gnomAD): Loss-of-function variants: 24 observed, 19.69 expected, observed/expected ratio (o/e) 1.22, 90% interval 0.88 to 1.7. The upper end of that interval is the gene's LOEUF score, 1.7, which puts it in group 6 of 6, group 1 being the genes least tolerant of losing a copy. Missense variants: 542 observed, 434.53 expected, observed/expected ratio (o/e) 1.25, 90% interval 1.16 to 1.34. Synonymous variants: 241 observed, 206.96 expected, observed/expected ratio (o/e) 1.16, 90% interval 1.05 to 1.3.
Gene-disease validity (ClinGen):
ClinGen rates the evidence that CCNO causes each of these diseases.
primary ciliary dyskinesia 29 (autosomal recessive): Definitive.
Homologues: Orthologues: chimpanzee CCNO (99% identical), macaque CCNO (96% identical), rabbit CCNO (91% identical), dog CCNO (90% identical), pig CCNO (87% identical), rat Ccno (81% identical), mouse Ccno (80% identical), guinea pig CCNO (74% identical), tropical clawed frog ccno (50% identical), tropical clawed frog XB940412 (29% identical), tropical clawed frog XB995740 (29% identical), tropical clawed frog ccnob.10 (29% identical), and 12 more. Paralogues in human: CCNA2 (24% identical), CCNA1 (23% identical), CCNB3 (22% identical), CCNB1 (21% identical), CCNB2 (21% identical), CCNP (19% identical), CCND3 (19% identical), CCNE2 (18% identical), CCNF (18% identical), CCNJ (18% identical), CCNE1 (18% identical), CCND1 (17% identical), and 6 more.
Diseases named in the same sentence as CCNO in open-access papers:
CCNO is named in the same sentence as 27 diseases in open-access papers, as found by Europe PMC text mining. Sharing a sentence is not in itself a finding about the gene and the disease. The quoted sentences say what the papers report.
Hydrocephalus (9 papers, 2015 to 2025). Hydrocephalus is an active distension of the ventricular system of the brain resulting from inadequate passage of CSF from its point of production within the cerebral ventricles to its point of absorption into the systemic circulation. "Ccno-deficient mice display gross hydrocephalus and mucociliary clearance defects and severe airway diseases as do CCNO mutations in humans." (PMID 25974046, 2015). "For example, there was a 10% increase in hydrocephalus in humans with a CCNO mutation." (PMID 39513856, 2024). "However, Ccno conditional and constitutive KO mice present hydrocephalus and/or infertility, two features occasionally observed in cyclin O-deficient patients." (PMID 32762766, 2020). "Collectively, our findings suggest that the alterations observed in ependymal cells caused by reduced levels of CCNO may reduce the reabsorption of CSF through a trans-ependymal pathway leading to the development of hydrocephalus." (PMID 29245899, 2017). "Our results further establish CCNO as an important gene for normal development and suggest that heterozygous CCNO mutations could underlie hydrocephalus or diminished fertility in some human patients." (PMID 29245899, 2017). "Our results suggest that residual activity of CCNO or genetic modifiers in some of the RGMC patient alleles identified may explain the incomplete penetrance of hydrocephalus and that heterozygous alleles of CCNO may cause pathologies in some human carriers of severe loss of function alleles." (PMID 29245899, 2017). "Moreover, it could indicate that haploinsufficiency of CCNO could underlie hydrocephalus or other defects in undiagnosed human patients." (PMID 29245899, 2017). "While genetic mouse models of PCD frequently develop hydrocephalus, patients with PCD hydrocephalus are sporadic, except those with mutations in FOXJ1, CCNO, P73, and MCIDAS, indicating developmental differences between rodents and humans." (PMID 38032388, 2024). "Pathogenic variants in CCNO and MCIDAS result in RGMC, hydrocephalus in some affected individuals, and severe respiratory phenotypes in some patients, with rapid deterioration in lung function reported." (PMID 34132502, 2021). "A conditional loss of-function model for murine Ccno showed that the mutant mice recapitulated the main cellular defects described in patients carrying CCNO mutations, and that lack of Ccno led to perinatal lethality due to the development of hydrocephalus." (PMID 29245899, 2017). "This could reflect roles for CCNO in the development or maintenance of adult tissues or be secondary to neurological deficits resulting from penetrant hydrocephalus." (PMID 29245899, 2017). "Genes like cyclin O (CCNO), NME/NM23 family member 7 (NME7), and huntingtin (HTT) are also involved in centriole amplification, γ-tubulin ring complex activity, and centrosomal organization, and their disruption can cause failure in cilia development and hydrocephalus." (PMID 40722587, 2025). "Recently, CCNO mutations were identified in a subset of Primary Ciliary Dyskinesia (PCD) patients affected by recurrent upper and lower airway infections that lead to the development of bronchiectasis and respiratory distress syndrome, as well as hydrocephalus (∼10%) and reduced fertility." (PMID 29245899, 2017). "CCNO expression is restricted to MCCs, and CCNO−/− mice exhibit characteristic features of MCC dysfunction, including hydrocephalus, mucociliary clearance deficit, and infertility." (PMID 35159149, 2022). "Moreover, hydrocephalus is frequently observed across murine motile-cilia gene knockouts (e.g., DNAH5, DNAAF1) but remains uncommon in human PCD except in rare ciliogenesis disorders (e.g., CCNO, FOXJ1), underscoring a rodent–human discrepancy." (PMID 41477643, 2025).
glioma (8 papers, 2015 to 2025). A benign or malignant brain and spinal cord tumor that arises from glial cells (astrocytes, oligodendrocytes, ependymal cells).
Infertility (4 papers, 2017 to 2024). "Human MCCs were also investigated in both sexes in cases of PCD and infertility: a male patient with an MCIDAS mutation and a female patient with CCNO mutation." (PMID 39513856, 2024). "GEMC1−/−, MCIDAS−/−, and CCNO−/− male mice are infertile, due to defective multicilia in the EDs." (PMID 35159149, 2022).
breast carcinoma (3 papers, 2018 to 2024). "We found that eight cyclins (CCNA2, CCNB1, CCNB2, CCND2, CCNE1, CCNE2, CCNF, CCNO) were differentially expressed between breast cancer and normal tissue samples, with the cut-off criterion of log2(fold change) >1, p < 0.05." (PMID 33791304, 2021).
lung carcinoma (3 papers, 2017 to 2022). "Moreover CCNO upregulation is significantly associated with reduced overall survival in lung cancer patients." (PMID 35941578, 2022). "Taken together, these results indicate that CCNO might be implicated in processes other than the proliferation and migration of lung cancer cells." (PMID 28860486, 2017). "Moreover, according to the Kaplan-Meier Plotter database, CCNO upregulation is significantly associated with a reduced overall survival of lung cancer patients, suggesting that CCNO is another orphan cyclin involved in the malignancy of the disease." (PMID 28860486, 2017). "Thirty one down-regulated genes are known to be prognostic markers of lung cancer, 28 of which are of favorable prognosis, such as GDPD1, SLC46A3, CLIC6, LZTS3 or CCNO." (PMID 36544755, 2022). "Median protein expression of CCNY, CCNO, CCNI, and CNTD2 was higher in lung cancer than normal lung tissue, but statistical significance was only found for CCNI and CNTD2." (PMID 28860486, 2017). "Confirming the results obtained of Western analysis, examining six pairs of lung cancer and paired adjacent normal tissue by immunohistochemistry demonstrated positive staining for CNTD2, CCNO and CCNI while adjacent normal lung was generally negative." (PMID 28860486, 2017).
cervical squamous cell carcinoma (2 papers, 2020 to 2023). A squamous cell carcinoma arising from the cervical epithelium. "A report have demonstrated that CCNO is overexpressed in cervical squamous cell carcinoma (CSCC) and RACK1/miR-302b/c/d-3p-mediated CCNO inhibition can dampen the progression of CSCC." (PMID 37124622, 2023).
ciliopathies (2 papers, 2021 to 2022). "We identified 10 genes (STK38L, TUBB2A/B, CCNO, ARL13B, RFX2, RAB23, TUBA1C, CEP170B, and SPATA7) that are established or candidate ciliopathy genes." (PMID 34485842, 2021).
colon cancer (1 paper, 2018). "Remarkably, the average expression of CNTD2 and CCNO was significantly higher in cancer tissues compared to their normal counterparts and, therefore, these cyclins were selected for further characterization in colon cancer cell lines." (PMID 30087414, 2018).
conductive hearing loss (1 paper, 2024). "Variants in CCDC114 cause sensorineural hearing loss (SNHL), while variants in CCNO, CDH3, DNAH5 and OFD1 cause conductive hearing loss (CHL)." (PMID 38818043, 2024).
endocervical adenocarcinoma (1 paper, 2020). An adenocarcinoma that arises from the endocervix. "The GEPIA database revealed a high expression of CCNO in CSCC and endocervical adenocarcinoma (p < 0.05)." (PMID 32792866, 2020).
lung disease (1 paper, 2022). "Other papers have also shown that CCNO is a key protein in lung physiology, and CCNO mutations result in lung disease." (PMID 35941578, 2022).
tumor (9 papers, 1982 to 2025). "A series of experiments were conducted to evaluate the effects of the RACK1/miR-302b/c/d-3p-CCNO axis in CSCC cell progression as well as tumor growth." (PMID 32792866, 2020). "The expression levels of CCNO were higher in tumour cell lines than in the normal one, while CCNY and CCNG1 exhibited higher expression in HT-29 cells." (PMID 30087414, 2018). "Importantly, overexpressed miR-302b-3p, miR-302c-3p or miR-302d-3p or RACK1 enhanced the apoptosis and suppressed the proliferation of CSCC cells in vitro, while inhibiting tumor growth in vivo by targeting CCNO." (PMID 32792866, 2020). "We detected positive staining in tumour tissue for CNTD2, that was mainly localized in the nuclei, and for CCNO, which appeared concentrated in a location compatible with the nucleoli of tumour cells." (PMID 30087414, 2018). "CNTD2 was predominantly localized to the nuclei of tumor cells, while the CCNI localized to the nuclear membrane and CCNO appeared concentrated in nucleoli." (PMID 28860486, 2017).
cancer (5 papers, 2017 to 2021). A tumor composed of atypical neoplastic, often pleomorphic cells that invade other tissues. "Aside from cancer cells, immune B cells require functional AhR to optimally proliferate, through activation of cyclin O." (PMID 33615198, 2021). "In addition, elevated mRNA expression of CCNO has been reported in GC tissues and depletion of CCNO can significantly induce cancer cell apoptosis both in vitro and in vivo, which is partially consistent with our findings." (PMID 32792866, 2020).
infection (1 paper, 2020). The state of being infected such as from the introduction of a foreign agent such as serum, vaccine, antigenic substance or organism. "At the same time, ciliary markers such as DNAH5, DNAAF5, MCIDAS, and CCNO were downregulated following infection of hNECs." (PMID 33409274, 2020). "Interestingly, DNAH5, MCIDAS, and CCNO exhibited consistent descending trends in all infections tested, suggesting this observation to be applicable to multiple respiratory viruses." (PMID 33409274, 2020).
CCNO also shares sentences with these, for which no sentence is quoted: primary ciliary dyskinesia (5 papers); glioblastoma (4); colorectal cancer (2); asthma (1); gastric cancer (1); lung adenocarcinoma (1); lymphoid tumor (1); malignant glioma (1); melanoma (1); myelosuppression (1); Neonatal respiratory distress (1); pleural mesothelioma (1); situs inversus (1).